SLC35E2B (solute carrier family 35 member E2B)
Description:
Putative transporter.
Synonyms: SLC35E2
Tractability: Antibody: UniProt predicts a signal peptide or a membrane-spanning region. PROTAC: ubiquitination databases record sites on it; its protein half-life has been measured.
Gene: Protein-coding gene on chromosome 1 (1,659,529 to 1,693,017, reverse strand). Ensembl gene ENSG00000189339.
Subcellular location: Membrane
Subcellular location (Human Protein Atlas): Nucleoplasm
Gene Ontology:
Cellular component: membrane
Genetic constraint (gnomAD): Loss-of-function variants: 18 observed, 23 expected, observed/expected ratio (o/e) 0.78, 90% interval 0.54 to 1.16. The upper end of that interval is the gene's LOEUF score, 1.16, which puts it in group 5 of 6, group 1 being the genes least tolerant of losing a copy. Missense variants: 244 observed, 324.63 expected, observed/expected ratio (o/e) 0.75, 90% interval 0.68 to 0.84. Synonymous variants: 127 observed, 141.78 expected, observed/expected ratio (o/e) 0.9, 90% interval 0.77 to 1.04.
Homologues: Orthologues: chimpanzee SLC35E2 (99% identical), macaque SLC35E2 (98% identical), dog SLC35E2B (87% identical), mouse Slc35e2 (86% identical), rat Slc35e2 (86% identical), guinea pig SLC35E2B (81% identical), pig SLC35E2B (81% identical), rabbit SLC35E2B (75% identical), tropical clawed frog slc35e2b (73% identical), zebrafish SLC35E2B (59% identical). Paralogues in human: SLC35E1 (25% identical), SLC35H1 (19% identical), SLC35E4 (18% identical), SLC35E3 (17% identical), SLC35C1 (15% identical), SLC35D2 (15% identical), SLC35D3 (15% identical), SLC35D1 (14% identical), SLC35D4 (12% identical).
Diseases named in the same sentence as SLC35E2B in open-access papers:
SLC35E2B is named in the same sentence as 1 disease in open-access papers, as found by Europe PMC text mining. Sharing a sentence is not in itself a finding about the gene and the disease. The quoted sentences say what the papers report.
myopia (1 paper, 2023). "In addition, exome sequencing identified SLC35E2B variants in Central European families with high myopia." (PMID 37449273, 2023).